ZEB1 (zinc finger E-box binding homeobox 1)
Diseases named in the same sentence as ZEB1 in open-access papers (continued):
Sharing a sentence is not in itself a finding about the gene and the disease.
ovarian carcinoma (continued). "Tissue transglutaminase (TG2), a multifunctional protein involved in cellular adhesion, promotes EMT in ovarian carcinoma by activating NF-κB complex, which induces Zeb1." (PMID 26356073, 2015). "Inducing epithelial-to-mesenchymal transition (EMT) in human ovarian cancer cells by overexpression of key transcription factors (Snail, Slug, Zeb1) or by acquiring drug resistance produces a similar increase in deformability." (PMID 26626154, 2015). "This is supported by the finding of elevated E-cadherin and reduced ZEB1 in metastatic epithelial ovarian cancer, as well as by our findings of overexpressed miR-200 family members and underexpression of ZEB1 and ZEB2 in metastatic HGSC." (PMID 24512620, 2014). "Several studies have proved that mRNA of ZEB1 was the target of miR-200c in different cancers, such as ovarian cancer and bladder cancer." (PMID 25277203, 2014). "Our data here showed the alteration of miR-150 in ovarian cancer cells led to opposite change of ZEB1, highlighting their negatively regulation." (PMID 25090005, 2014). "To demonstrate that miR-101 is an endogenous regulator of ZEB1 and ZEB2 in ovarian carcinoma cells, we transfected SKOV3 ovarian cancer cells with miR-101 or miR-Ctrl followed by measurement of ZEB1 and ZEB2 mRNA and protein at 48 h after transfection." (PMID 24677166, 2014). "This study demonstrates a novel mechanism in which FGF2 down-regulates E-cadherin expression through the activation of PI3K/Akt/mTOR and MAPK/ERK signaling, and the up-regulation of Slug and ZEB1 in human ovarian cancer cells." (PMID 23554977, 2013). "In this study, we report that FGF2 treatment down-regulated E-cadherin by up-regulating its transcriptional repressors, Slug and ZEB1, in human ovarian cancer cells." (PMID 23554977, 2013). "Our data suggest that MAPK/ERK is an upstream factor of ZEB1 activation in ovarian cancer cells in vitro." (PMID 23554977, 2013). "In ovarian cancer cell lines, certain miRNAs have been associated with the invasive and metastatic phenotype.The miR-200 family contributes to metastasis in ovarian cancer by targeting ZEB1 and ZEB2m, which in turn activate the transcription of E-cadherin." (PMID 23109879, 2012). "This concept is supported by the observation that expression of ZEB1 becomes estrogen independent in aggressive endometrial and ovarian carcinomas." (PMID 22190929, 2011). "Moreover, NEAT1 upregulation controls ZEB1 expression via miR-194 to help ovarian cancer cells resist paclitaxel through drug resistance." (PMID 40165339, 2025). "Interestingly, Zinc finger E-box-binding homeobox 1 (ZEB1) mediates abnormal expression of SLC3A2 in inducing chemoresistance to cisplatin in ovarian cancer cells." (PMID 38705513, 2024). "Similarly, inhibition of miR-429 led to drug resistance development via influencing ZEB1 expression in epithelial ovarian cancer." (PMID 38152652, 2023). "ZEB1-mediated tumor promotion was due to upregulation of circANKRD17 in ovarian cancer." (PMID 38152652, 2023). "LncRNA NEAT1 conferred paclitaxel resistance via regulation of miR-194/ZEB1 axis in ovarian cancer." (PMID 38152652, 2023). "The transcription factor ZEB1 has been reported to be involved in EMT in ovarian cancer." (PMID 38152652, 2023). "For example, ZEB1 promotes chemoresistance to cisplatin by suppressing SLC3A2 in ovarian cancer." (PMID 36512117, 2022). "ZEB1 was also investigated in publicly available ovarian cancer gene-expression datasets." (PMID 35794446, 2022). "It is our hope that markers like ZEB1 could be useful in determining which ovarian cancers are likely to respond to platinum retreatment." (PMID 35794446, 2022). "Among the targets regulated by miR-124, we could isolate at least six genes (PDCD6, ROCK1, SLUG, STAT3, TGF-β, ZEB1) common to several epithelial cancers, including lung, stomach, hepatocellular, breast, and ovarian cancers." (PMID 36362406, 2022). "ZEB1 was individually predictive of overall survival in ovarian cancer." (PMID 35794446, 2022).
ovarian carcinoma (continued). "Our previous study showed that ovarian cancer cells induced to have mesenchymal phenotype either by overexpression of EMT transcription factors (ZEB1, SNAI1, and SNAI2), oncogenes (H-Ras v12), or by drug resistance were all consistently more deformable than cells with epithelial phenotype." (PMID 33330495, 2020). "CD44 was knocked down by small interfering RNA, the expression of Snail, ZEB1, and Caveolin-1 in a stable Snail-expressing ovarian cancer cell line HO8910PM-Snail (HOPM-Snail) and its control cell line HO8910PM-vector (HOPM) was detected by western blotting analysis." (PMID 31497537, 2019). "Among those factors with a significant reduction in their mRNA levels, we noticed that EMT-associated transcription factors ZEB1 and ZEB2 were much lower in ISL-treated SKOV3 cells than untreated ones, further indicating the deterrence of EMT by ISL in ovarian cancer cells." (PMID 31623144, 2019). "Synchronously, ZEB1 was found to induce chemoresistance to PTX in ovarian cancer." (PMID 31793989, 2019). "Thus, a partial downregulation of Zeb1 in either cancer cells or stromal cells of the tumor microenvironment is enough to completely block the malignant progression of lung, colon and ovarian carcinomas in Zeb1 (+/-) mice." (PMID 30304480, 2018). "However, the role of EMT and MET related events associated with ZEB1, ZEB2, E-cadherin, vimentin and miR-200 family is highly complex, which certainly requires further investigation in the context of endometriosis and ovarian cancer." (PMID 26819681, 2015). "In addition, a previous study has reported that the overexpression of Gab2 activates the epithelial-mesenchymal transition program through activation of the PI3K/Zeb1 pathway, and inhibits the expression of E-cadherin in a subset of ovarian cancer." (PMID 26095858, 2015). "Third, overexpression of miR-150 could dramatically inhibit the cell proliferation and motility of ovarian cancer cells in vitro and substantially suppress the protein expression of ZEB1." (PMID 25090005, 2014). "Forth, ZEB1 was identified as a direct target of miR-150, and knock-down of ZEB1 in ovarian cancer cells could mimic the inhibition of cell proliferation, migration and invasion by miR-150." (PMID 25090005, 2014). "We also confirmed that miR-150 could block migration and invasion of ovarian cancer cells by targeting ZEB1, which would constitute a promising target for rational cancer therapy." (PMID 25090005, 2014). "MiR-200c has been described as a powerful master regulator of epithelial-to-mesenchymal transition in breast and ovarian cancer cells through altering the expression of ZEB1 and E-cadherin by binding to 3’ UTRs and driving degradation or blocking translation of the target mRNA." (PMID 24204560, 2013). "However, in experiments on ten breast and ovarian carcinoma cell lines, upregulation of the zeb1 gene was seen in only one cell line, suggesting that the zeb1 mRNA response in neoplastic cells has become deranged." (PMID 21324165, 2011). "Furthermore, resistin accelerates the EMT process in ovarian cancer cells by decreasing the expression of the epithelial cell marker E-cadherin and boosting the expression of the mesenchymal cell markers ZEB1 and Vimentin, thereby encouraging cancer cells to migrate." (PMID 36694280, 2023). "ZEB1 may be useful as a marker for platinum retreatment in recurrent ovarian cancer." (PMID 35794446, 2022). "ZEB1, best known for driving an epithelial-to-mesenchymal transition (EMT) in cancer cells to promote tumor progression, is required by tumor-associated macrophages (TAMs) for their tumor-promoting and chemotherapy resistance functions in a mouse model of ovarian cancer." (PMID 33519933, 2021). "However, the underlying mechanism of ZEB1/miR-200 axis activation in ovarian cancer progression is still not clear." (PMID 33188287, 2020). "Presumably, CD44 may regulate chemoresistance of ovarian cancer via ZEB1." (PMID 31497537, 2019).
ovarian carcinoma (continued). "Also, all ovarian cancer cell lines with high ZEB1 expression were positive for NNMT." (PMID 28412735, 2017). "Indeed, elevated Slug and ZEB1 mRNA levels have been found in ovarian carcinoma." (PMID 23554977, 2013). "A key factor in ovarian cancer progression is epithelial–mesenchymal transition (EMT), regulated by Twist1, Snail, and Zinc finger E-box binding homeobox 1 (ZEB1), which increase cell motility and invasion." (PMID 41373772, 2025). "In ovarian cancer cells, it has been demonstrated that fibroblast growth factor (FGF2) results in increased expression of SLUG and ZEB1 by activating the PI3K/AKT/mTOR and MAPK/ERK signaling pathways." (PMID 40678416, 2025). "Non-coding RNA Regulation in Ovarian Cancer: MicroRNAs (miR-203a-3p, etc.)and long non-coding RNAs (such as OIP5-AS1) regulate ZEB1 and other epithelial–mesenchymal transition-related genes through epigenetic mechanisms to promote ovarian cancer metastasis." (PMID 40732683, 2025). "NEAT1 acts as a ceRNA in oncogenic cells, targeting miR-101-3p and enhancing the expression of ZEB1, resulting in the proliferation of ovarian cancer cells, tumour growth and apoptosis of CD8+ cells via miR-101-3p/ZEB1/PD-L1 pathway." (PMID 40176927, 2024). "Our result demonstrated that both EMT transcription factors (Snail, ZEB1, Twist) and EMT protein markers (Vimentin) were responds to FSH in epithelial ovarian cancer cells." (PMID 38505602, 2024). "DAB2 expression had significant positive correlations with mesenchymal markers (ZEB2, TGFβ1, SNAI2, ZEB1, FN1, MMP2, TWIST1 and MMP3) and CSC markers (CD44 and MYD88) in ovarian cancer cell lines (CCLE) and tissues (TCGA: RNA sequencing and microarray)." (PMID 37815603, 2023). "The authors suggest that ZEB1 and FOXM1 are significant in ERBB2 signaling for peritoneal metastasis of ovarian cancer." (PMID 37324014, 2023). "In ovarian cancer cells, overexpressing of HK2 enhanced cell motility by inducing of EMT-related proteins, such as CDH2, fibronectin, MMP9, ZEB1, ZEB2 and vimentin." (PMID 35953860, 2022). "circ-CSPP1 has been shown to reduce the inhibitory effect of miR-1236-3p on ZEB1 to promote EMT and ovarian cancer development." (PMID 33858418, 2021). "LncRNA PTAR has been shown to regulate ZEB1 expression by competitive binding of miR-101-3p to promote EMT, invasion, and metastasis in ovarian cancers." (PMID 33858418, 2021). "In an attempt to elucidate the mechanisms controlling ovarian cancer progression, in the present study we have identified ET-1/ETAR signaling in the regulation of the ZEB1/miR-200 circuit." (PMID 33188287, 2020). "Here, we discover that miR-200b/c, besides targeting ZEB1, specifically bind the ETAR mRNA and reduce its expression in ovarian cancer cells." (PMID 33188287, 2020). "Therefore, the knowledge of the complex ZEB1/miRNA interplay, established by functional links with other signaling pathways, may provide mechanistic insight into the regulatory networks controlling ovarian cancer aggressiveness and metastatic progression." (PMID 33188287, 2020). "In ovarian cancer cells, miR-1271 inhibits EMT via ZEB1 down-regulation (binding into 3′-UTR), leading to the decreased viability, proliferation, invasion, and migration of tumor cells." (PMID 32664703, 2020). "The present study shows that ETAR/ZEB1 targeting by miR-200 heightens ET-1 signaling and consequently can generate a condition of ETAR addiction in ovarian cancer cells." (PMID 33188287, 2020). "Our data also showed that ZEB1, Snail, and Caveolin-1 are regulated by CD44, indicating the crucial role of CD44 in the initiation of EMT in ovarian cancer." (PMID 31497537, 2019). "ISL also reduced the metastasis of ovarian cancer and extended the life span of animals bearing SKOV3/Luc cells by blocking the EMT process and regulating the expression of ZEB1." (PMID 31623144, 2019).
ovarian carcinoma (continued). "Collectively, these findings suggest that ISL inhibited ovarian cancer EMT and intraperitoneal xenograft development through the inhibition of ZEB1." (PMID 31623144, 2019). "In ovarian cancer, NEAT1 contributed to paclitaxel resistance partly through upregulating ZEB1 expression by sponging miR-19441." (PMID 30894512, 2019). "MiR-591 have important roles in several tumors such, as miR-591 confers PTX resistance to ovarian cancer cells and modulation of MiR-591 resensitises PTX-resistant cancer cells by targeting ZEB1." (PMID 31049030, 2019). "We not only observed an increase in vimentin in the ovarian cancer cells in our study, but further confirmed the EMT induction through increase in another mesenchymal marker, ZEB1, with a simultaneous decrease in the epithelial marker, e-cadherin." (PMID 30131543, 2018). "In a previous study, miR-101 had been shown to suppress EMT by targeting ZEB1 and ZEB2 in ovarian carcinoma." (PMID 30098599, 2018). "The same group also profiled mesothelial clearance–competent and –incompetent ovarian cancer cell lines and concluded that mesenchymal genes, including SNAI1, ZEB1, and TWIST1 are enriched in the clearance-competent cells." (PMID 29861857, 2018). "Our studies define a novel ZEB1/NNMT signaling axis, which elicits mesenchymal gene expression, as well as phenotypic and metabolic plasticity in ovarian cancer cells upon chronic glucose starvation." (PMID 28412735, 2017). "In summary, our results suggest that the ZEB1/NNMT signaling axis induces phenotypic and metabolic plasticity, as well as mesenchymal gene expression in ovarian cancer cells upon chronic glucose deprivation." (PMID 28412735, 2017). "Recently, LPA was elucidated to stimulate the epithelial-to-mesenchymal switch in ovarian cancer cells via downregulation of SIRT1, an established inactivator of ZEB1 and suppressor of EMT." (PMID 28792442, 2017). "In our panel of ovarian cancer cell lines, NNMT protein expression positively correlated with expression of ZEB1 and other mesenchymal markers, such as vimentin." (PMID 28412735, 2017). "Re-expression of miRNAs of the miR-200 family reduced expression of its target genes, including ZEB1, ZEB2, FN1 and class III β-tubulin (TUBB3), and inhibited ovarian cancer cell migration and invasion." (PMID 28399108, 2017). "Overexpression of Gab2 reduced expression of E-cadherin and increased Zeb1 expression and cell migratory and invasive abilities through the activation of the PI3K pathway in ovarian cancer cells." (PMID 26356073, 2015). "The novel Gab2/PI3K/Zeb1 pathway can be targeted by PI3K and mammalian target of rapamycin (mTOR) inhibitors and can be potentially used to treat Gab2-driven ovarian cancer in combination with standard chemotherapy." (PMID 26095858, 2015). "MiR-106a and miR-591 have important roles in conferring paclitaxel resistance to ovarian cancer cells, and modulating miRNAs to resensitize paclitaxel-resistant cancer cells by regulating BCL10, caspase-7, and ZEB1." (PMID 25887170, 2015). "In conclusion, we demonstrated for the first time that miR-101 can directly target ZEB1 and ZEB2, resulting in suppression of the EMT in ovarian carcinoma." (PMID 24677166, 2014). "Taken together, our findings indicate that FGF2 differentially regulates Slug and ZEB1 expression via the PI3K/Akt/mTOR and MAPK/ERK signaling pathways in human ovarian cancer cells." (PMID 23554977, 2013). "Since there was an affect on adhesion to BMC and laminin in ovarian cancer cells with high miR-200c levels, we performed the adhesion assay with the Hec50 and MDA-MB-231 cells in which ZEB1 had been stably knocked down." (PMID 20049172, 2010). "Notably, JIB-04 modulates ZEB1, a key regulator of epithelial-mesenchymal transition (EMT), which drives aggressive traits in ovarian cancer, including invasion and metastasis." (PMID 40664642, 2025). "Inhibition of ZEB1 reduced cell migration, invasion, EMT and proliferation in ovarian cancer." (PMID 38152652, 2023).
ovarian carcinoma (continued). "ZEB1 has been upregulated by TGF-β and ZEB2 by TGF-β treatment of ovarian cancer cells." (PMID 36766756, 2023). "In this study, further study also demonstrated that HK2 could elevate the expression of EMT-related factors in human ovarian cancer cell, like fibronectin, MMP9, CHD2, Vemintin, ZEB1 and ZEB2." (PMID 35953860, 2022). "Additionally, the positive correlation between HK2 and fibronectin, MMP9, CHD2, Vimentin, ZEB1 and ZEB2 in human ovarian cancer were confirmed from the GEPIA online database (p < 0.05)." (PMID 35953860, 2022). "ZEB1 has the potential to be used as biomarker of overall prognosis in ovarian-cancer patients but not of platinum/taxane chemoresistance." (PMID 35794446, 2022). "Additionally, the positive correlation between HK2 and fibronectin, MMP9, CHD2, Vemintin, ZEB1 and ZEB2 in human ovarian cancer were also confirmed from the GEPIA online database." (PMID 35953860, 2022). "In contrast, ZEB1 was not predictive of overall survival when the dataset of ovarian-cancer patients was limited to those confirmed to be treated with platinum chemotherapy ((HR = 1.04, n = 622, p = 0.35)." (PMID 35794446, 2022). "In a search of the complex regulatory networks driving ovarian cancer metastatization, in this study we identify a miR-200b/c-dependent circuit established between ETAR and ZEB1 that is regulated by ET-1 to induce invasive cell behavior fostering metastatic progression." (PMID 33188287, 2020). "In addition, miR-200 overexpression significantly inhibits ovarian cancer cell invasiveness and metastasis by downregulating MMP3, possibly through ZEB1/pSMAD3 signaling." (PMID 32256980, 2020). "The double-negative feedback loop between miR-200 family members and ZEB1 in ovarian carcinoma represents a molecular switch regulating the fine-tuning and reversibility of EMT18." (PMID 33188287, 2020). "Moreover, our previous report on a panel of 43 ovarian cancer cell lines also showed that SNAI1 expression is enriched in cell lines with E and IE phenotypes, whereas expressions of TWIST1 and ZEB1/2 are higher in cell-line IM and M phenotypes." (PMID 32370157, 2020). "Furthermore, suppression of ZEB1 reduced PXT resistance in PTX-resistant GC cells, in accordance with ovarian carcinoma cells." (PMID 31793989, 2019). "Thus, E-Cadherin, P-Cadherin, Zeb1, HMGA2, Rab25, CD24, NCAM (CD56), Sox11 and Vimentin expression was assessed in 100 advanced-stage ovarian cancer patients undergoing platinum-based chemotherapy." (PMID 29389895, 2018). "The miR-200 family plays a critical role in the suppression of epithelial-to-mesenchymal transition (EMT) and tumor cell migration, invasion, and metastasis by directly targeting ZEB1 and ZEB2 transcription factors and the level of miR-200s are important regulators of EMT in ovarian cancer cells." (PMID 29389895, 2018). "Recent observations have provided convincing evidence to suggest that miR-200 family members (miR-200a, miR-200b, miR-200c, miR-141, and miR-429) and miR-205 can activate EMT by targeting the EMT drivers ZEB1 and ZEB2 in various cancer types, including ovarian cancer." (PMID 27612152, 2016). "To further investigate the mechanism by which C17orf91 elicited its oncogenic role, we explored whether C17orf91 could regulate key pro-metastatic genes, such as KLF8, MYC, SNAI2, TWIST1, ZEB1 and ZEB2 in ovarian cancer." (PMID 27535740, 2016). "Here, we designed small-scale siRNA screens targeting these six mesenchymal signature genes (CD99L2, EMP3, ITGA5, SYDE1, VIM, ZEB1) to explore their functional relevance and their roles during EMT reversal by nintedanib (BIBF1120) in a mesenchymal-like SKOV3 ovarian cancer cell line." (PMID 26061747, 2015). "ZEB1 and ZEB2, validated targets of miR-141 and miR-200c, contribute to epithelial- mesenchymal transition and cancer cell migration in cancer cell lines and ovarian cancer specimens." (PMID 25815280, 2015).